U6 (U6 spliceosomal RNA )
Gene: Small nuclear RNA gene on chromosome 16 (72,376,704 to 72,376,760, forward strand). Ensembl gene ENSG00000283564.
Gene Ontology:
Molecular function: U4 snRNA binding
Biological process: formation of quadruple SL/U4/U5/U6 snRNP; spliceosomal tri-snRNP complex assembly
Cellular component: U4/U6 x U5 tri-snRNP complex; U6 snRNP
Homologues: Paralogues in human: RNU6-187P (93% identical), RNU6-38P (93% identical), RNU6-658P (93% identical), RNU6-838P (93% identical), RNU6-1011P (91% identical), RNU6-1251P (91% identical), RNU6-1322P (91% identical), RNU6-247P (91% identical), RNU6-329P (91% identical), RNU6-331P (91% identical), RNU6-338P (91% identical), RNU6-33P (91% identical), and 1286 more.